HIF1A (hypoxia inducible factor 1 subunit alpha)
Diseases named in the same sentence as HIF1A in open-access papers (continued):
Sharing a sentence is not in itself a finding about the gene and the disease.
gastric cancer (continued). "A number of studies has identified high expression of HIF-1α in gastric cancer and various other cancers, and it is found to be closely associated with the biological behavior of tumors." (PMID 29267502, 2017). "Our qRT-PCR results showed the expression of AM, VEGFA, NDRG3, and HIF-1α allincreased, though to different degrees, and at different times, in the gastric cancer cell lines." (PMID 29179449, 2017). "We have previously reported a highly efficient functional inactivation of HIF-1α in the gastric cancer cell lines AGS and MKN28 via lentiviral transduction of small hairpin RNAs (shRNA)." (PMID 26760764, 2016). "Here, we show that the transcription of a long non-coding RNA (lncRNA), Gastric Adenocarcinoma Associated, Positive CD44 Regulator, Long Intergenic Non-Coding RNA (GAPLINC), is directly activated by HIF-1α in gastric cancer (GC)." (PMID 27729869, 2016). "In conclusion, our study illustrated miR-421, a HIF-1α induced miRNA, played an important role in gastric cancer." (PMID 27016414, 2016). "To further elucidate the function of HIF-1α in gastric cancer, we investigated the effect of CoCl2 on cisplatin-treated SGC-7901 and AGS cell motility via transwell assay." (PMID 27016414, 2016). "Ectopic expression of miR-186 suppresses proliferation and glycolytic metabolism of gastric cancer cells mainly by HIF-1α." (PMID 27159677, 2016). "Functional characterization of these cells identified HIF-1α as pivotal for the malignant phenotype of gastric cancer." (PMID 26760764, 2016). "MiR-186 suppresses cell proliferation induced by hypoxia inducible factor 1 alpha (HIF-1α) in gastric cancer cell lines MKN45 and SGC7901." (PMID 27159677, 2016). "These clinical observations reinforce the cancer-specific targeting ability of NIRF dye as well as the activate roles of HIF1α/OATPs in mediating dye uptake in gastric cancer." (PMID 27329598, 2016). "Although the fast energy supply mode was attenuated by HIF-1α knockdown, the trends were consistent with gastric cancer cell survival." (PMID 27159677, 2016). "In gastric cancer, HIF-1α and HIF-2α levels are higher in metastasis samples compared with non-metastatic ones." (PMID 25590810, 2015). "The present study examined the association between HIF-1α and Wnt/β-catenin in vitro in the SGC-7901 gastric cancer cell line." (PMID 25997455, 2015). "OPN has been reported to promote invasion and metastasis of gastric cancer through HIF-1α upregulation and MMP9 activation." (PMID 25872762, 2015). "We previously established HIF-1α knockdown (KD) cells and control (SC) cells in the 58As9 gastric cancer cell line." (PMID 26339797, 2015). "This is also confirmed in the present study, suggesting that autophagy defect induced nuclear translocation of NF-κB increases HIF-1α mRNA and protein levels in gastric cancer cells." (PMID 26497999, 2015). "In the present study, the expression of HIF-1α, MMP-2, MMP-9, bFGF and uPA was detected in order to further reveal the underlying mechanism of the function of the KAI1 gene in gastric cancer." (PMID 26622792, 2015). "The present study suggested that in gastric cancer cells, HIF-1α has a role both upstream and downstream of the Wnt/β-catenin signaling pathway, and that these pathways have a reciprocal regulative function." (PMID 25997455, 2015). "We have also noticed several new-ly-publicated meta analyses of estimating prognostic value of either HIF-1α or Survivin on gastric cancer patient." (PMID 24647137, 2014). "In fact, in our study as well, the survival rate in gastric cancer in the HIF-1α expression group was lower." (PMID 23558457, 2014).
gastric cancer (continued). "The median frequency for the subset of proteins expressed in gastric cancer was 54.1% (range, 38.9–80.2%) for HIF-1α, 61.2% (range, 40.7–3.9%) for CD44v6, 55.6% (range, 34.5–76.3%) for Survivin, and 43.3% (range, 20.0–70.2%) for PTEN." (PMID 24647137, 2014). "In this study, we found that the overexpression of HIF-1α occurred at a median frequency of 54.1% in gastric cancer." (PMID 24647137, 2014). "Our analyses, combining 8 independent studies that included 923 patients and 898 controls, revealed that HIF-1α overexpression was frequently observed in patients with gastric cancer compared to the counterpart normal tissue." (PMID 24647137, 2014). "We observed a positive correlation between HIF-1α expression and gastric cancer peritoneal dissemination (GCPD) in gastric cancer patients." (PMID 25142304, 2014). "Our group has previously shown that RhoE as a direct target for HIF-1α and mediates hypoxia-induced epithelial to mesenchymal transition in gastric cancer cells." (PMID 24312338, 2013). "After histological confirmation of gastric cancer (upper-left and down-left), we investigated the expression of HIF-1α and Foxp3 by immunohistochemistry in 99 patients." (PMID 23723999, 2013). "In their study, rapamycin treatment effectively blocked the HIF-1α activation in a gastric cancer cell line under hypoxia and reduced the size of the CD-31-positive vessel area, leading to decreased tumor growth in a subcutaneous implantation model." (PMID 24216696, 2013). "In gastric cancer, various mechanisms of invasion and metastasis activated by hypoxia/HIF-1α have been reported." (PMID 24216696, 2013). "Our results are consistent with previous reports that high levels of HIF1α reduced the effectiveness of cytotoxic agents in lung and gastric cancer cell lines." (PMID 23342109, 2013). "Our group previously established two gastric cancer cell lines, MKN45-KD and MKN74-KD, with a deficient HIF-1α expression using siRNA transfection." (PMID 24216696, 2013). "Several studies have identified HIF-1α target genes related to cancer invasion/metastasis in gastric cancer." (PMID 24216696, 2013). "In gastric cancer patients, HIF-1α activation following extended hypoxia strongly correlates with an aggressive tumor phenotype and a poor prognosis." (PMID 24216696, 2013). "They showed that inhibition of HIF-1α via RNA interference results in the upregulation of α5 integrin on the cell surface of gastric cancer cells, whereas other integrins remain unaffected." (PMID 24216696, 2013). "This review briefly summarizes the crucial roles that HIF-1α plays in the glucose metabolism, carcinogenesis, angiogenesis, invasion, metastasis, anoikis and chemoresistance in gastric cancer." (PMID 24216696, 2013). "At present, few reports have argued for the implication of HIF-1α in radioresistance using gastric cancer cells." (PMID 24216696, 2013). "Strikingly, gastric cancer patients with high HIF-1α had poorer survival than those with low HIF-1α, which further strengthened our proposal that HIF-1α, or rather hypoxia, is connected with the progression of gastric cancer." (PMID 23723999, 2013). "Immunohistochemistry was performed on gastric cancer tissues obtained from 152 patients who underwent curative resection to assess the expression of hypoxia-inducible factor-1α (HIF-1α), glucose transporter-1 (GLUT-1), hexokinase-2 (HK-2) and PDK-1." (PMID 23135628, 2013). "This article argues for the critical roles of HIF-1α in glucose metabolism, carcinogenesis, angiogenesis, invasion, metastasis, cell survival and chemoresistance, focusing on gastric cancer." (PMID 24216696, 2013). "HIF-1α knockdown (KD) and control (SC) gastric cancer cells, which were established using the MKN45 and MKN74 cell lines, were studied." (PMID 23181099, 2012). "In the present study, we silenced the function of HIF-1α to evaluate its role in the peritoneal dissemination of gastric cancer cell lines." (PMID 23181099, 2012).
gastric cancer (continued). "Compared with gastric cancers, cervical cancers tend to have higher levels of HIF1A indicating hypoxia response, although equally high levels in non-malignant cervical mucosa raise the possibility of ex vivo stimulation of this oxygen-sensing factor." (PMID 22929309, 2012). "This study was performed to clarify the role of hypoxia-inducible factor-1 α (HIF-1α) in the development of peritoneal dissemination in a xenograft mouse model of gastric cancer." (PMID 23181099, 2012). "In the present study, we first compared the development of peritoneal dissemination in the peritoneal cavity of nude mice between HIF-1α KD and control (SC) gastric cancer cell lines." (PMID 23181099, 2012). "In order to confirm the correlation between HIF-1α and NF-κB observed in the clinical gastric cancer samples, we produced stable SNU-668 cell lines overexpressing either empty vector (SNU-668Vector) or IκBαM (SNU-668IκBαM)." (PMID 21119667, 2011). "In gastric cancer, both HIF-1α and NF-κB have been reported to be overexpressed in surgical samples." (PMID 21119667, 2011). "Using three gastric cancer cell lines, we first analyzed the effect of NF-κB on the oxygen-dependent degradation of HIF-1α protein." (PMID 21119667, 2011). "To confirm the correlation between HIF-1α and NF-κB in human gastric cancer tissues, we performed immunohistochemistry on tissue array slides containing 251 human gastric cancer specimens." (PMID 21119667, 2011). "Although, in a previous study, we demonstrated that both pFOXO1 and HIF-1α were constitutively over-expressed in gastric cancer, the correlation between these transcription factors has not been reported in human cancer." (PMID 21696576, 2011). "Nuclear expressions of HIF-1α and NF-κB/RelA were assessed in 251 human gastric carcinoma specimens by immunohistochemical tissue array analysis." (PMID 21119667, 2011). "The present study investigated the correlation between HIF-1α and NF-κB RelA in 251 surgically excised human gastric carcinoma tissues." (PMID 21119667, 2011). "Previous studies reported a reactivation of the proapoptotic factor Bid, or a change in the balance of pro- and antiapoptotic Bcl-2 family members to account for increased apoptosis rates following inactivation of HIF-1α in drug-treated gastric cancer cells." (PMID 20706634, 2010). "A contribution of HIF-1α to chemoresistance of neoplastic cells has been observed in a wide spectrum of solid tumors, including gastric cancer." (PMID 20706634, 2010). "Here, we identify HIF-1α as a powerful determinant of chemosensitivity in gastric cancer cells under normoxic conditions." (PMID 20706634, 2010). "Our current data suggests that HIF-1α similarly guards gastric cancer cells against chemotherapy-induced senescence under normoxic conditions." (PMID 20706634, 2010). "In a complementary pharmacological approach, we used the HIF-1α-inhibitor 2-methoxy-estradiol (2ME2) to investigate its effect on the migratory and adhesive ability of gastric cancer cells." (PMID 19223895, 2009). "We provide experimental evidence for reduced metastatic properties of gastric cancer cells through functional inactivation of HIF-1α, even under conditions of ambient oxygen." (PMID 19223895, 2009). "Our results show a potent inhibiting effect of 2ME2 on protein expression and activity of HIF-1α in gastric cancer cells." (PMID 19223895, 2009).
gastric cancer (continued). "The role of HIF-1α for the malignant progression of gastric cancer was studied in vitro by using the two human gastric cancer cell lines AGS and MKN28." (PMID 19223895, 2009). "To determine if HIF-1α is involved in gastric cancer cell motility, we compared the migratory and invasive capacity of HIF-1α KD and control cells." (PMID 19223895, 2009). "In support of this scenario, the recent data show that human gastric cancer is associated with marked increase in expression of lactate dehydrogenase-5 (LDH-5), in correlation with HIF-1α, VEGF and COX-2." (PMID 19564950, 2009). "Treatment of subcutaneous xenografts of the human gastric cancer cell line NCI-H87 in nude mice with an HIF-1α-inhibiting compound resulted in smaller and less vascularised tumours." (PMID 19223895, 2009). "Others have found that inhibition of HIF-1α in human gastric cancer TMK-1 cells markedly retarded the tumor growth, angiogenesis, and vessel maturation." (PMID 19564950, 2009). "In sharp contrast, 90% of analysed gastric cancer samples showed positivity for HIF-1α specifically over the nuclei of neoplastic epithelial cells." (PMID 19223895, 2009). "Against this background and given the widespread expression of HIF-1α in human gastric cancer samples, it seems justified to include 2ME2 (or other equally effective HIF-1α-inhibiting agents) in study protocols against gastric cancer." (PMID 19223895, 2009). "Taken together, we performed a detailed analysis of the role of HIF-1α for human gastric cancer in vitro and in vivo." (PMID 19223895, 2009). "To explore the functional role of HIF-1α for the metastatic capacity of human gastric cancer cells, we designed a lentiviral-mediated RNA-interference system to knockdown HIF-1α in vitro." (PMID 19223895, 2009). "We first examined the effects of 2ME2 treatment on HIF-1α protein in the gastric cancer cell line AGS." (PMID 19223895, 2009). "Given the widespread acceptance of HIF-1α as a positive regulator of cellular proliferation, we characterised the consequences of HIF-1α inhibition on gastric cancer growth." (PMID 19223895, 2009). "Inhibition of HIF-1α by means of RNA interference or chemical compounds has proven antitumoural activity in two murine gastric cancer models." (PMID 19223895, 2009). "To determine the effects of HIF-1α inactivation on gastric cancer progression, we developed a lentivirus-based system for stably expressing siRNA against HIF-1α." (PMID 19223895, 2009). "Our functional analysis of the role of HIF-1α in the pathogenesis of human gastric cancer comprised central characteristics of metastatic cells, namely migration, invasion and adhesion to endothelial cells." (PMID 19223895, 2009). "Taken together, these results show that our lentivirus-based siRNA system lead to a strong and stable inactivation of HIF-1α in a different panel of human gastric cancer cell lines." (PMID 19223895, 2009). "More recently, we have shown increased expression of HIF-1α in gastric cancer development and in adenocarcinoma vs dysplasia in the Barrett's oesophageal cancer sequence." (PMID 18283323, 2008). "Although the median follow-up duration was too short to analyze, HIF-1α expression was found to be a poor prognostic factor for disease recurrence or progression in patients with gastric cancer." (PMID 18452596, 2008). "HIF-1α expression was a poor prognostic factor of disease recurrence or progression in patients with gastric cancers." (PMID 18452596, 2008). "In contrast, two further studies in gastric cancer showed HIF-1α expression was an adverse prognostic factor in multivariate analyses." (PMID 17179985, 2007). "They used either pharmacological or genetic inhibition of HIF-1α, which resulted in dramatic effects on tumour vascularisation and reduced growth of xenografts derived from human gastric cancer cells." (PMID 17179985, 2007).
gastric cancer (continued). "We examined the relationship between HIF-1α and p21 expression, apoptosis and tumor progression using tissue specimens obtained surgically from 126 patients with gastric cancer." (PMID 17166265, 2006). "In the present study, we examined the role of HIF-1α in hypoxic control of tumor progression, by examining the relationship between HIF-1α expression, p21 expression and apoptosis in tissue specimens from patients with gastric cancer." (PMID 17166265, 2006). "In conclusion, the combination of B7H3 and HIF-1α may serve as a novel prognostic biomarker for gastric cancer and also holds potential as a therapeutic target for its treatment." (PMID 41710663, 2026). "Additionally, chromatin immunoprecipitation (ChIP) and luciferase reporter gene assays indicated that HIF-1α promotes apoptosis in gastric cancer cells, with LINC00511 overexpression resulting in decreased apoptosis." (PMID 40861273, 2025). "In addition, inhibiting the upstream regulatory factors of HIF-1α is also helpful for the treatment of gastric cancer." (PMID 40563539, 2025). "MicroRNA-519c inhibits autophagy in gastric cancer cells by specifically targeting HIF-1α." (PMID 40004215, 2025). "Targeting HIF-1α could improve the efficacy of radiotherapy and immunotherapy in gastric cancer, providing new therapeutic possibilities." (PMID 41220952, 2025). "Studies on the cystic adenoid salivary gland and gastric cancer have shown that HIF-1α expression and hypoxic conditions are common in these tumor models and that this characteristic is related to the level of aggressiveness in these tumors, in addition to their resistance to treatment." (PMID 40149887, 2025). "Our study also confirmed the normoxic expression of HIF1α in various cell lines of gastric cancer." (PMID 40469197, 2025). "HIF-1α acts as a significant factor in the occurrence and development of gastric cancer." (PMID 40563539, 2025). "Similarly to gastric cancer, inhibiting the upstream signaling pathways of HIF-1α in liver cancer cells can also effectively delay the proliferation of liver cancer cells." (PMID 40563539, 2025). "For example, in gastric cancer, the transcription of lncRNA GAPLINC is directly regulated by HIF-1α activation, a mechanism associated with cancer progression, suggesting that GAPLINC has potential as a liquid biopsy tool to assist in guiding clinical treatment decisions." (PMID 40861273, 2025). "Diallyl trisulfide, a garlic-derived chemical, suppresses HIF-1α transcription in stomach cancer." (PMID 40004215, 2025). "Taken together, these results demonstrate that the TNFα/NF-κB/HIF-1α pathway may contribute to CD204+ M2-like TAMs-dependent induction of miR-210 expression in gastric cancer cells." (PMID 38175202, 2024). "In gastric cancer, hypoxia and HIF-1α play significant roles in tumour growth and chemoresistance." (PMID 39816318, 2024). "NAT10/SEPT9/HIF‐1α positive feedback loop regulates glucose metabolism in gastric cancer." (PMID 39640362, 2024). "Consequently, H19 plays a regulatory role in gastric cancer (GC) angiogenesis through the YTHDF1/SCARB1 axis, offering additional insights into the mechanism underlying HIF‐1α/H19/YTHDF1/SCARB1 regulation in GC angiogenesis." (PMID 39135292, 2024). "Since the PI3K/AKT/mTOR/HIF-1α axis drives tumour-promoting inflammation in H. pylori- and EBV-associated gastric cancer, agents that target this pathway may also inhibit the development of premalignant gastric lesions from completing malignancy." (PMID 39816318, 2024). "NRF2 knockdown blocked HIF-1α and HO-1 upregulation, further suppressing gastric cancer survival." (PMID 38424190, 2024). "Similarly, in gastric cancer(GC), HIF-1α can be reduced by knocking down IGF2BP, which in turn achieves the effect of controlling the malignant growth of cancer cells." (PMID 39033180, 2024).